TRPC6 (transient receptor potential cation channel subfamily C member 6)
Diseases named in the same sentence as TRPC6 in open-access papers (continued):
Sharing a sentence is not in itself a finding about the gene and the disease.
diabetic nephropathy (continued). "TRPC6 may contribute to the pathogenesis of diabetic nephropathy, a common complication in subjects with diabetes." (PMID 32872338, 2020). "In addition, several studies suggest that inhibitors of TRPC6 transcription ameliorate albuminuria and the histologic features of diabetic kidney disease in rodent models." (PMID 31877991, 2019). "Although selective blockade of TRPC6 was only modestly beneficial in diabetic kidney disease, it is possible that inhibition of multiple TRPC family members might be a more effective approach." (PMID 31877991, 2019). "In support of a role for TRPC6 in diabetic nephropathy, glomerular expression of TRPC6 is upregulated in kidneys from rodent models of diabetes, and knockdown of TRPC6 in cultured podocytes both inhibits hyperglycemia-induced apoptosis and preserves podocin expression." (PMID 31877991, 2019). "Tetrandrine could alleviate podocyte injury induced by TRPC6 overexpression, decrease 24 h urine protein and glomerular cell proliferation in the membranous glomerulopathy, and restrain diabetic process and renal damage in diabetic nephropathy." (PMID 35836957, 2022). "However current therapy of kidney disease almost always entails the use of multiple agents, and it is possible that TRPC6 inhibition would be more effective if other targets were simultaneously blocked, especially in the case of diabetic nephropathy or hypertension." (PMID 36421724, 2022). "These events have been reported involving several mechanisms, including NOX4/TRPC6, Ang II/TRPC6/NFAT pathways, and the rearrangement of the actin cytoskeleton in the podocytes in diabetic nephropathy." (PMID 33377622, 2021). "Furthermore, podocyte-associated markers including TRPC6 have been found increased in diabetic nephropathy urine samples and correlated with albuminuria, suggesting that TRPC6 mRNA may represent another clinical biomarker of podocyturia in diabetic nephropathy." (PMID 34012910, 2015). "On the other hand, upregulated TRPC6 channels inhibit the signal transducers and activators of transcription (STAT) signaling and promote proliferative and inflammatory processes in tubular cells in diabetic nephropathy." (PMID 36613622, 2022). "However, in a model of streptozotocin (STZ)-treated Dahl Salt-sensitive (Dahl SS) rats, deletion of TRPC6 had a protective effect in diabetic kidney disease, protecting the podocytes but not the glomerulus as a whole." (PMID 32872338, 2020). "While there is strong evidence that glomerular TRPC6 channels are dysregulated in diabetic nephropathy (DN), there is no consensus as to whether deletion or inactivation of TRPC6 is protective in animal models of DN." (PMID 32123821, 2019). "Thus, it is possible inhibition of TRPC6 may not be sufficient to ameliorate diabetic nephropathy but might potentiate effects of other therapeutic strategies." (PMID 36421724, 2022).
diabetes (24 papers, 2012 to 2025). "Angiotensin II (Ang II) levels are found to be elevated in diabetes; furthermore, it was reported that Ang II causes activation of TRPC6 in podocytes." (PMID 26656101, 2015). "The presence of diabetes, urinary nephrin, TRPC6, and podocin significantly increased the risk of albuminuria in the univariate analysis." (PMID 24103534, 2013). "TRPC6 is post-translationally regulated, but a role for O-linked β-N-acetyl glucosamine (O-GlcNAcylation) as elevated by diabetes, is unknown." (PMID 36936781, 2023). "Hyperfiltration is usually seen very early during diabetes even before the onset of microalbuminuria, and the accompanying increase in glomerular capillary pressure would be expected to cause an increase in TRPC6 activation in podocytes." (PMID 36421724, 2022). "TRPC6 knockout in type 2 diabetes mellitus induced hepatic inflammation and fibrosis, inhibited calcium overload, and suppressed the calcineurin/nuclear factor of activated T cells 2/NLRP3 signaling pathway in mice." (PMID 41450741, 2025). "Diabetes increases the expression of TRPC6 in podocytes in vivo while reducing podocyte autophagy flux TRPC6 gene knockout can reduce the progression of DKD." (PMID 39619610, 2024). "Overall, these observations complicate the direct conclusions from Ca2+ imaging experiments about TRPC6 channel activity and its role in diabetes." (PMID 37108424, 2023). "In podocytes from rats with diabetes, we observed that basal TRPC6 activity was slightly increased (NPomax30 = 0.5 ± 0.1), while the influence of Ca2+ store depletion on TRPC6 activity was negligible (NPomax30 = 0.3 ± 0.1)." (PMID 37108424, 2023). "In db/db mice, KL overexpression inhibited TRPC6 expression and attenuated diabetes-induced podocyte injury, which was accompanied by decreased albuminuria and ameliorated glomerulosclerosis." (PMID 35480629, 2022). "Avoiding RH is essential for glycemic control in patients with diabetes, and TRPC6/GLUT3 represents potent targets for delaying the onset of dementia in patients with diabetes." (PMID 35077394, 2022). "In consistence, the response of TRPC6 expression in hippocampus of mice with type 1 diabetes mellitus (DM) to recurrent moderate hypoglycemic (RH) episodes was similar to that in PC12 cells." (PMID 33135341, 2020). "Here, we observed that the expression of TRPC6 in hippocampus was inhibited by RH in the case of diabetes, and TRPC6 knockout showed similar deteriorate effects on cognitive function as RH in the diabetic model." (PMID 33135341, 2020). "Our laboratory also examined the effects of whole body TRPC6 knockout in Akita mice, a type 1 model of diabetes." (PMID 31877991, 2019). "We observed that TRPC blocker reduced H2S-induced hyperalgesia in diabetic rats, TRPC6 protein was overexpressed during the diabetes development and NaHS enhanced TRPC6 protein expression in diabetic rats." (PMID 30602386, 2019). "We showed that the urinary mRNA of TRPC6 was higher in diabetes subjects than in controls and was positively correlated with albuminuria and HbA1c." (PMID 24103534, 2013). "Trpc6 may play an important role in contributing to the interaction of diabetes and hypertension to promote kidney injury." (PMID 40641971, 2025). "However, a recent publication has questioned the protective role of TRPC6 KO against DN in Sprague–Dawley rats injected with a high dose of streptozotocin (STZ) used to induce type 1 diabetes mellitus." (PMID 37108424, 2023). "GLP-1 agonists, such as liraglutide, reduce the expression of glomerular TRPC6 in STZ-induced diabetes in Sprague Dawley rats and may act to reduce interactions between TRPC6 and NADPH oxidases." (PMID 36421724, 2022). "Thus, ROS generated by NADPH oxidase-4 leads to mobilization of TRPC6 in podocytes and NOX4 knockout is protective in STZ-induced diabetes and is associated with markedly reduced Ca2+ influx in podocytes from diabetic Dahl SS rats." (PMID 36421724, 2022).
diabetes (continued). "It is possible that the increased albuminuria in diabetes is not TRPC6 related, although some studies have indicated that diabetes alone, in the absence of HTN, does not cause marked increases in kidney injury, similar to our results." (PMID 34866402, 2022). "During diabetes development, the expression level of TRPC6 channels and agonist-stimulated Ca2+ response is increased, which might lead to the basal accumulation of Na+ within the cell, cell depolarization and an earlier contribution of Ca2+ influx through NCX." (PMID 37108424, 2023). "Interestingly, normoalbuminuric subjects with diabetes showed high mRNA levels of nephrin, TRPC6, and alpha actinin-4 relative to controls, suggesting that podocyte damage may occur early in DN, as has been reported by others." (PMID 24103534, 2013). "TRPM5 and TRPA1 activation can improve insulin secretion and negatively correlate with T2DM development, whereas TRPC6, TRPV4 and TRPM2 antagonism can slow down diabetes progression." (PMID 38659380, 2024). "Nephroseq analysis revealed increased expression of HIF1α, ZEB2, and TRPC6 in Nakagawa CKD dataset and Hodgin Diabetes Mouse Glomeruli datasets." (PMID 31784544, 2019). "We found that experimental diabetes increased TRPC6, but not TRPV1 nor TRPA1, protein expression in DRG." (PMID 30602386, 2019). "Lastly, hyperglycemia may contribute to kidney injury in diabetes by promoting NOX-dependent ROS generation and, in turn, activation of TRPC6." (PMID 31877991, 2019). "Therefore, it has been somewhat surprising that TRPC6 knockout by itself does not produce sustained renoprotection in rodent models of diabetes." (PMID 36421724, 2022). "The data in this study and those obtained previously are consistent with a model in which the absence of functional TRPC6 allows podocytes to withstand this chronic stress more effectively (although, for unknown reasons, this did not occur during diabetes)." (PMID 33918778, 2021). "Thus far, no clinical studies have measured TRPC6 gene expression in the urine of diabetes subjects with incipient or overt nephropathy." (PMID 24103534, 2013). "Additionally, in this study, we found that RH and/or TRPC6 knockout caused cognitive impairments under diabetic condition, and the cognitive improvement effect of hyperforin was absent in TRPC6−/− mice, indicating that TRPC6 repression by RH is critical for the cognitive impairment in diabetes." (PMID 33135341, 2020).
glomerulosclerosis (24 papers, 2010 to 2026). A hardening of the kidney glomerulus caused by scarring of the blood vessels. "Consistent with this, podocyte-specific expression of disease-causing TRPC6 mutations, especially TRPC6-M131T, results in albuminuria and glomerulosclerosis albeit less than occurs in humans with a homologous mutation." (PMID 36421724, 2022). "Meanwhile, a steady-state expression of TRPC6, a known pathogenic factor of glomerulosclerosis, is increased through a pathway dependent on NFATc1." (PMID 29038896, 2018). "Dysfunctions of TRPC6 are implicated in the pathogenesis of various cardiovascular and kidney conditions such as vasospasm and glomerulosclerosis." (PMID 24709960, 2014). "We assume that activated TRPC6 feels the damage signal in adriamycin-induced glomerulosclerosis, and then activates downstream factors, causing the disappearance of the foot process, then changes in the glomerular filtration barrier, ultimately led to the occurrence of proteinuria." (PMID 29619864, 2018). "Moreover, in vivo evidence from NFATc1nuc transgenic mice and Akita mice showed NFAT activation-induced podocyte apoptosis and injury, and NFAT-dependent TRPC6 expression, the mutations of which have been shown to be associated with proteinuria and glomerulosclerosis in human patients." (PMID 22778954, 2012). "Traditional histology-based phenotyping of podocyte number, glomerulosclerosis, and tissue fibrosis was performed from harvested Pod-GCaMP5/tdTomato TRPC6-Tg mouse kidneys in the 3 treatment groups." (PMID 39226116, 2024). "A significant protective effect of TRPC6 inactivation on the severity of glomerular damage (glomerulosclerosis) was ascertained by semi-quantitative analysis of light microscopic images." (PMID 37615749, 2023). "TRPC6 knockout reduced glomerulosclerosis in this disease model as ascertained by semi-quantitative analysis of light microscopic images." (PMID 36421724, 2022). "TRPC6 inactivation also produced a similar reduction in glomerulosclerosis in anti-GBM models of autoimmune glomerulonephritis and in aging in Sprague Dawley rats." (PMID 35805070, 2022). "In silico annotation of the SNP function showed that rs1938859 is located in the 5′ untranslated region of the TRPC6 gene and was reported as an expression quantitative trait locus (eQTL) of the same gene, which is related to glomerulosclerosis." (PMID 35448080, 2022). "In summary, we have shown that global TRPC6 inactivation in rats results in a histologically discernible reduction in glomerulosclerosis in aging animals." (PMID 33918778, 2021). "This is consistent with a previous report that soluble klotho reduces glomerulosclerosis in part by the suppression of TRPC6 expression on the podocyte cell surface." (PMID 33918778, 2021). "On the other hand, TRPC6 inactivation resulted in reduced glomerulosclerosis in an autoimmune model of rapidly progressing glomerulonephritis in rats but did not reduce renal cortical inflammation or tubulointerstitial fibrosis in that model." (PMID 33918778, 2021). "Knockout TRPC-6 in Akita mice attenuated glomerulosclerosis, tubular injury, and proteinuria while even promoting mesangial cell expansion." (PMID 34326888, 2021). "In most studies, TRPC6 knock-out animals showed markedly reduced glomerulosclerosis and podocyte foot effacement." (PMID 34830371, 2021). "In support of this possibility, podocyte-specific overexpression of TRPC6 in vivo promotes proteinuria and modest glomerulosclerosis." (PMID 31877991, 2019). "We found that knockout of TRPC6 significantly reduced proteinuria, tubule dilation, and casts, and markedly reduced the severity of glomerulosclerosis." (PMID 31877991, 2019). "In contrast, systemic knockout of TRPC6 significantly reduced glomerulosclerosis and attenuated the decrease in the podocyte marker podocin observed in wild type rats." (PMID 31877991, 2019).
glomerulosclerosis (continued). "Our study showed that the expression of glomerular TRPC6 was significantly increased when glomerulosclerosis occurred." (PMID 29619864, 2018). "Previous studies have attempted to determine if TRPC6 contributes to kidney dysfunction and glomerulosclerosis using genetic manipulations of TRPC6 in mice." (PMID 29785489, 2018). "Our purpose is to survey the effect of ATRA on dynamic changes of TRPC6 expressions in glomerulosclerosis rat model, in-depth understanding the molecular mechanism of glomerulosclerosis, and the special therapeutic effects of ATRA on proteinuria." (PMID 29619864, 2018). "There are several lines of evidence that sustained activation of TRPC6 channels in podocytes contributes to foot process effacement and glomerulosclerosis." (PMID 27630573, 2016). "SuPAR activates podocyte αvβ3 integrin and receptor for advanced glycation end-products, now identified as an obligate coreceptor, triggering a Rac1/NOX2-Src-TRPC6 (transient receptor potential canonical channel 6) cascade that produces proteinuria and glomerulosclerosis." (PMID 42313902, 2026). "Moreover, podocyte-specific over-expression of wild-type or mutant TRPC6 channels in mice resulted in glomerulosclerosis and albuminuria indicating that the dysfunction of TRPC6 channels in podocytes is sufficient to drive kidney disease." (PMID 35805070, 2022). "Moreover, when those animals were crossed with TRPC6 knockout mice the resulting albuminuria and glomerulosclerosis significantly was reduced, consistent with the conclusions of the studies carried out in rats." (PMID 36421724, 2022). "Moreover, in the chronic PAN model, CRISPR/Cas9-mediated inactivation of TRPC6 resulted in robust reductions in albuminuria, uremia, azotemia, glomerulosclerosis, foot process effacement, and tubulointerstitial fibrosis." (PMID 35805070, 2022). "ROS induces glomerulosclerosis with the upregulation of the TRPC6 in podocytes." (PMID 34326888, 2021). "Moreover, proteinuria and glomerulosclerosis were observed in mice over-expressing wild-type or mutant TRPC6 channels in podocytes or in mice with podocyte-specific mutations in heterotrimeric G proteins that lead to constitutive activation of TRPC6." (PMID 27630573, 2016). "ATRA may activate downstream factors by blocking TRPC6 signal, so be able to maintain the structural and functional integrity of glomerular filtration barrier, and play a protective role in antiproteinuria and glomerulosclerosis." (PMID 29619864, 2018). "One important drug target are TRPC6 channels which are physiologically activated by DAG after Gq protein-mediated stimulation of PLCβ and which play a major pathophysiological role in many diseases, including glomerulosclerosis and pulmonary hypertension." (PMID 35365606, 2022). "In this study, the effects of TRPC6 knockout on glomerulosclerosis were not specifically evaluated, and the downstream effector pathways of CaMKII were not further explored." (PMID 31877991, 2019). "In this study, we measured TRPC6 expression levels in the adriamycin-induced glomerulosclerosis rats with or without ATRA treatments." (PMID 29619864, 2018). "However, in those models, the inactivation of TRPC6 did not reduce albuminuria or tubulointerstitial disease, in spite of the reductions in glomerulosclerosis." (PMID 35805070, 2022). "However, it is currently not known how TRPC6 influences glomerulosclerosis, a growing body of evidence points out that harmful intracellular effects caused by increased cation flux cannot be ignored." (PMID 29619864, 2018).